GIP (gastric inhibitory polypeptide)
Diseases named in the same sentence as GIP in open-access papers (continued):
Sharing a sentence is not in itself a finding about the gene and the disease.
polycystic ovary syndrome (3 papers, 2025). A disorder that manifests as multiple cysts on the ovaries. "Polycystic ovary syndrome (PCOS) is linked to a higher risk of T2D and is reportedly associated with increased GIP and lower GLP-1 responses to meal ingestion or to an oral glucose load, in agreement with the often elevated BMI in these individuals." (PMID 40024571, 2025).
adrenal hyperplasia (2 papers, 2023 to 2024). "Genetics: It is now clear that there are no KDM1A (lysine demethylase 1A) germline mutations in acromegalic patients, like in gastric inhibitory polypeptide (GIP, alternatively named glucose-dependent insulinotropic polypeptide)-dependent primary bilateral macronodular adrenal hyperplasia." (PMID 39194755, 2024).
Alcohol Use Disorder (2 papers, 2023 to 2025). "Further RCTs are needed to fully explore the therapeutic potential of GLP-1 agonists and GIP/GLP-1 combination drugs for the treatment of Alcohol Use Disorder." (PMID 38017205, 2023).
anorexia nervosa (2 papers, 2020 to 2026). A disorder most often seen in adolescent females characterized by a refusal to maintain a minimally normal body weight, an intense fear of gaining weight, a disturbance in body image, and, in postmenarcheal females, the development of amenorrhea. "While some studies in mice suggest that incretins like GLP-1 and GIP may have a beneficial effect on bone, a negative association between bone formation markers and PYY has been reported among adolescents with anorexia nervosa." (PMID 32545353, 2020).
Arrhythmia (2 papers, 2016 to 2025). Any cardiac rhythm other than the normal sinus rhythm. "The evidence for GLP‐1 RAs, dual GLP‐1/GIP RAs, and other incretin‐based therapies in HFrEF remains limited and inconclusive, with concerns about potential adverse effects such as arrhythmias and worsening HF." (PMID 41309245, 2025). "Our results suggest that the mechanisms of sitagliptin-induced anti-arrhythmias were related to an attenuated NGF expression through a resistin-dependent pathway, and that the resistin expression was coupled to the regulation of GIP." (PMID 26811539, 2016).
asthma (2 papers, 2024 to 2025). "On the contrary, there were fewer respiratory and asthma-like events with tirzepatide, a dual agonist of the GIP and GLP-1 receptors." (PMID 39768911, 2024). "However, the association between GLP-1 and GIP/GLP-1 receptor agonists and asthma is not unambiguous." (PMID 39768911, 2024).
Atrophy (2 papers, 2022 to 2023). Any weakening or degeneration, especially through lack of use. "Regarding histology, 66.7% of the GIP+ patients had atrophy compared to 32.7% of the GIP patients (p-value 0.01)." (PMID 36904257, 2023). "In addition, GHP and GIP are more likely to happen in the gastric mucosa of patients with long-term chronic gastritis or atrophy." (PMID 35875116, 2022).
celiac disease (2 papers, 2023 to 2025). An autoimmune genetic disorder with an unknown pattern of inheritance that primarily affects the digestive tract. "The peptide hormone levels of cholecystokinin (CCK, from I cells), glucose-dependent insulinotropic polypeptide (GIP, from K cells), and GLP-1 (from L cells) are reduced in the blood of celiac disease patients." (PMID 37240181, 2023).
Cirrhosis (2 papers, 2020 to 2025). A chronic disorder of the liver in which liver tissue becomes scarred and is partially replaced by regenerative nodules and fibrotic tissue resulting in loss of liver function. "The results reported by Junker showed that non-diabetic patients with NAFLD have normal secretion of GIP and GLP-1, but a reduced incretin effect, although patients with cirrhosis have elevated concentrations of GIP and GLP-1, and a reduced incretin effect." (PMID 32069846, 2020).
colorectal cancer (2 papers, 2023 to 2025). A primary or metastatic malignant neoplasm that affects the colon or rectum. "This limitation is notable given evidence from experimental models where glucose-dependent insulinotropic peptide (GIP) agonists, such as tirzepatide, have been shown to promote tumor proliferation in a dose-sensitive manner, particularly in colorectal cancer cell lines." (PMID 41310711, 2025).
cystic fibrosis (2 papers, 2025 to 2026). Autosomal recessive disorder caused by pathogenic variants in the CFTR gene (cystic fibrosis transmembrane conductance regulator), which encodes a chloride and bicarbonate channel expressed in epithelial cells, and follow the diagnosis criteria. "Collectively, these findings highlight the therapeutic potential of targeting GIP signaling to preserve bone mass in conditions such as hypoparathyroidism and cystic fibrosis." (PMID 41596254, 2026).
endothelial dysfunction (2 papers, 2015 to 2023). In vascular diseases, endothelial dysfunction is a systemic pathological state of the endothelium (the inner lining of blood vessels) and can be broadly defined as an imbalance between vasodilating and vasoconstricting substances produced by (or acting on) the endothelium. "Genes indicated by 16 shared risk loci point to mechanisms with potential roles in migraine pathogenesis and CAD, including endothelial dysfunction (PHACTR1) and insulin homeostasis (GIP)." (PMID 27066539, 2015).
hepatorenal syndrome (2 papers, 2010 to 2023). Hepatorenal syndrome is a form of impaired kidney function that occurs in individuals with advanced chronic liver disease. "They observed an increased expression of GIP in cases of renal insufficiency." (PMID 20673334, 2010).
hyperplasia (2 papers, 2021 to 2022). An abnormal increase in the number of cells in an organ or a tissue with consequent enlargement. "Hyperplasia caused an increase in the number of GLP-1- and GIP-secreting cells, thus contributing to the increase in their secretion." (PMID 33450994, 2021).
hypoparathyroidism (2 papers, 2024 to 2026). Hypoparathyroidism is an endocrine disorder in which the parathyroid glands in the neck do not produce enough parathyroid hormone (PTH). "In one study including four female patients with postsurgical hypoparathyroidism, s.c. injection of 100 μg GIP markedly reduced plasma CTX levels despite very low or undetectable PTH concentrations, indicating that its antiresorptive effect does not rely on PTH-mediated pathways." (PMID 41596254, 2026). "However, the antiresorptive effect of GIP is preserved in overweight or hypoparathyroidism individuals, suggesting that GIP affects bone metabolism independently of PTH." (PMID 38725663, 2024).
insomnia (2 papers, 2023 to 2025). A sleep disorder characterized by difficulty in falling asleep and/or remaining asleep. "Genome-wide association studies identified a genetic locus (near ATP5G1, UBE2Z, SNF8, IGF2BP1 and GIP) linked to insomnia and CVD." (PMID 40176577, 2025).
malnutrition (2 papers, 2025). Inadequate nutrition resulting from poor diet, malabsorption, or abnormal nutrient distribution. "Furthermore, no studies have examined the association between GiP and markers of malnutrition in pregnancy, such as mid-upper arm circumference (MUAC), and no studies have investigated the relationship between GiP and nutritional status before pregnancy or in early first trimester." (PMID 40038683, 2025).
memory impairment (2 papers, 2020 to 2021). "Recently, GLP-1 and GIP analogues have been reported to inhibit the memory impairment and cognitive dysfunction in neurodegenerative diseases." (PMID 34851228, 2021). "Several studies have demonstrated that GLP-1 alleviated learning and memory dysfunction and that a GLP-1 analogue and GIP analogue prevented memory impairments." (PMID 32032367, 2020).
mental disorder (2 papers, 2025). A disease that has its basis in the disruption of mental process. "In addition, GLP-1 RAs and GIP RAs have robust effects on comorbidities that differentially affect persons with mental disorders (eg, cardiovascular, cerebrovascular, and metabolic disorders) and psychotropic drug-related weight gain." (PMID 39964126, 2025). "Herein, we propose that GLP-1 RAs and GIP RAs are promising transdiagnostic mechanistically informed therapeutics in the treatment and prevention of multiple domains of psychopathology, including general cognitive, reward, and motivation systems and mental disorders." (PMID 39964126, 2025).
myocardial ischemia (2 papers, 2022 to 2023). A disorder of cardiac function caused by insufficient blood flow to the muscle tissue of the heart. "However, very little is known about GIP metabolism in the acute phase of myocardial ischemia or for stable patients with CAD, which constitutes a direction for future research." (PMID 35205155, 2022).
peripheral arterial disease (2 papers, 2022). A disorder of the arteries supplying the upper and lower extremity and the visceral organs. "In this study, the association between GIP levels and CAD and PAD (peripheral artery disease) were also assessed." (PMID 35205155, 2022). "In mice LPS and IL-1b administration directly induced GIP secretion and patients with peripheral arterial disease (PAD) showed higher circulating GIP levels compared to patients without PAD." (PMID 35123462, 2022).
pituitary adenoma (2 papers, 2024 to 2025). "Further studies are needed to establish the connection between oral food intake, GIP/GIPR axis, and the development of pituitary adenoma." (PMID 37344722, 2024).
sarcopenia (2 papers, 2023 to 2025). Progressive decline in muscle mass due to aging which results in decreased functional capacity of muscles. "In a study of GIP receptor-knockout mice, researchers discovered that GIP drives the differentiation of fibroadipogenic muscle precursors into adipocytes, which is thought to be the pathological cause of sarcopenia." (PMID 41515907, 2025). "GIP may promote adipogenic differentiation of muscle precursor cells, contributing to sarcopenia; thus, GIPR antagonism has been proposed as a potential therapeutic approach for sarcopenia management." (PMID 41515907, 2025). "This study aimed to explore whether genetic and pharmacological gastric inhibitory polypeptide (GIP) receptor antagonism suppresses IMAT accumulation and ameliorates sarcopenia in mice." (PMID 37897141, 2023). "However, GIP has non-negligible side effects on muscle cells, and GIPR antagonism could be used as a new treatment for sarcopenia." (PMID 41515907, 2025).
acne (1 paper, 2024). An inflammatory process of the sebaceous glands which is characterized by comedones, nodules, papules and/or pustules on the skin. "One study analyzed the circulating levels of GLP-1 and other incretins such as gastric inhibitory polypeptide in high-risk acne patients." (PMID 38586157, 2024).
adrenocortical cancer (1 paper, 2014). "In this study, we transiently transfected the human GIPR expression vector into cultured human adrenocortical carcinoma cells (H295R) and treated them with GIP to examine the direct link between GIPR activation and steroidogenesis." (PMID 25334044, 2014). "We showed the upregulation of the mRNA level of POMC, a precursor of ACTH, and MC2R in the GIP-treated and GIPR-expressing H295R adrenocortical cancer cell line." (PMID 25334044, 2014).
adrenocortical tumor (1 paper, 2014). "These suggest that GIPR is not only ectopically expressed in the adrenocortical tumor, but also is activated by GIP after each meal, resulting in periodic cortisol secretion." (PMID 25334044, 2014).
Allergy (1 paper, 2025). An allergy is an immune response or reaction to substances that are usually not harmful. "Although u-GIP may serve as a robust biomarker, its clinical use in individuals with gluten sensitivity or allergy requires careful consideration." (PMID 40977729, 2025).
anemia (1 paper, 2025). A reduction in the number of red blood cells, the amount of hemoglobin, and/or the volume of packed red blood cells. "GiP was also associated with lower hemoglobin and anemia during pregnancy and lower folate in the third trimester." (PMID 40038683, 2025). "Our results support previous findings that GiP is an important indicator of iron deficiency and anemia during pregnancy; however, our study only found an association between GiP initiation and hemoglobin changes from the first, and not from the second, trimester." (PMID 40038683, 2025). "Although our study also found that women with GiP consistently had lower hemoglobin, individual changes might be more significant when they relate to the absence and presence of anemia." (PMID 40038683, 2025).
angina pectoris (1 paper, 2022). The symptom of paroxysmal pain consequent to MYOCARDIAL ISCHEMIA usually of distinctive character, location and radiation. "We hope that GIP and GLP-1 will soon permanently enter the canon of drugs used for CAD-management, also in non-diabetic patients, reducing mortality and the risk of reinfarction or hospitalization for angina pectoris." (PMID 35205155, 2022).
anxiety disorder (1 paper, 2022). A category of psychiatric disorders which are characterized by anxious feelings or fear often accompanied by physical symptoms associated with anxiety. "In the central nervous system (CNS), studies of GIP are mainly focused on neurodegenerative diseases; hence, little is known about the functions of GIP in chronic pain and pain-related anxiety disorders." (PMID 35712239, 2022).
Atherosclerotic lesion (1 paper, 2012). A lesion associated with atherosclerosis, a multifactorial and multipart progressive disease manifested by the focal development within the arterial wall of lesions, that ranges from the development of a fatty streak, plaque progression, and plaque disruption. "Moreover, CXCL1, CXCL9, β-NGF, C-peptide, GIP and adiponectin are higher only in CHC patients in agreement with previous studies in which these molecules were found elevated only in diabetic patients with complications (nephropathy, retinopathy and atherosclerotic lesions)." (PMID 22745767, 2012).
atrial fibrillation (1 paper, 2026). A disorder characterized by an electrocardiographic finding of a supraventricular arrhythmia characterized by the replacement of consistent P waves by rapid oscillations or fibrillatory waves that vary in size, shape and timing and are accompanied by an irregular ventricular response. "Therapeutic interventions promoting lymphangiogenesis, either through VEGFC administration or weight loss intervention by LY3437943 (the novel triple GIP, GLP-1, and glucagon receptor agonist), significantly attenuate atrial fibrillation inducibility." (PMID 42156758, 2026).
bone fracture (1 paper, 2012). "So far it has been shown that sitagliptin improves fatty liver, that GIP contributes to bone metabolism, and, from a meta-analysis, that the risk of bone fracture is significantly reduced in patients treated with DPP-4 inhibitors." (PMID 23024732, 2012).
brain injury (1 paper, 2018). Acute and chronic (see also brain INJURIES, CHRONIC) injuries to the brain, including the cerebral hemispheres, CEREBELLUM, and brain STEM. "We have previously shown the neuroprotective activity of GIP in an animal model of traumatic brain injury." (PMID 29641447, 2018). "GIP plasma assays: In the present study, human GIP was assayed in plasma at two different doses in the Alzet pump, one of which used in the experiments described here and a second, lower dose used in our previous study on traumatic brain injury." (PMID 29641447, 2018).
Cerebral ischemia (1 paper, 2024). Restriction of arterial blood supply to the brain associated with insufficient oxygenation to support the metabolic requirements of the tissue. "Treatment with a GLP-1/GIP dual agonist hampered ER stress and apoptosis in diabetic rats with cerebral ischemia-reperfusion injury as well." (PMID 39795860, 2024).
Cholecystitis (1 paper, 2025). The presence of inflammatory changes in the gallbladder. "Cholecystitis was similarly reduced in the GLP/GIP cohort (0.8% vs. 2.2%), with an RR of 2.736 (95% CI: 2.239–3.344) and HR of 1.847 (95% CI: 1.501–2.274; p < 0.001)." (PMID 41464784, 2025).
choledocholithiasis (1 paper, 2025). Presence or formation of gallstones in the common bile duct. "Choledocholithiasis was also reduced in the GLP-1/GIP cohort (0.6% vs. 1.5%; RR 2.72, 95% CI 2.14–3.46; HR 1.90, 95% CI 1.48–2.44; p < 0.001)." (PMID 41464784, 2025). "For choledocholithiasis, a protective association was again observed, with events occurring in 0.6% of GLP/GIP users versus 1.5% of non-users (RR = 2.722, 95% CI: 2.140–3.463; HR = 1.902, 95% CI: 1.483–2.439; p < 0.001)." (PMID 41464784, 2025).
cholelithiasis (1 paper, 2025). The presence of crystallized deposits forming in the gallbladder or biliary tree, primarily composed of cholesterol, bilirubin, and bile. "Cholelithiasis occurred in 3.5% of GLP-1/GIP users compared with 6.3% of nonusers (risk ratio [RR] 1.81, 95% CI 1.64–2.00; hazard ratio [HR] 1.27, 95% CI 1.14–1.41; p < 0.001)." (PMID 41464784, 2025). "Cholelithiasis occurred significantly less frequently among GLP/GIP users (3.5%) compared with non-users (6.3%), corresponding to a risk ratio (RR) of 1.811 (95% CI: 1.636–2.004) and a hazard ratio (HR) of 1.269 (95% CI: 1.140–1.413; p < 0.001)." (PMID 41464784, 2025).
chronic bronchitis (1 paper, 2022). A type of chronic obstructive pulmonary disease characterized by chronic inflammation in the bronchial tree that results in edema, mucus production, obstruction, and reduced airflow to and from the lung alveoli. "In the group of patients with chronic bronchitis, adiponectin, TNFa and GIP levels were 1.4 times higher." (PMID 36291711, 2022).
co-infections (1 paper, 2021). "QIAstat-Dx GIP identified co-infections in 36 (28.8%) specimens." (PMID 33963926, 2021). "Interestingly, GI prevalence (68.8%) and co-infection (28.8%) rates determined by QIAstat-Dx GIP were remarkably higher than those reported in previous syndromic testing studies on paediatric study populations." (PMID 33963926, 2021).
diabetic retinopathy (1 paper, 2024). "The role of endogenous GIP and TZP in the development of diabetic retinopathy is unknown in humans, while experiments in diabetic rats are limited to the description of GIP and GIP receptor expression in the retina." (PMID 39141075, 2024).
duodenal ulcer (1 paper, 2025). An ulcer in the duodenal wall. "While switching from semaglutide (a GLP-1 agonist) to tirzepatide (a GIP/GLP-1 co-agonist) worsened symptoms, including nausea and epigastric pain, ultimately leading to acute duodenal ulcer perforation, exact contributing factors are unclear." (PMID 40236372, 2025).
dyspepsia (1 paper, 2025). An uncomfortable, often painful feeling in the stomach, resulting from impaired digestion. "GIP, an enzyme involved in intestinal physiological functions, can influence the mucosal immune system, permeability, and enteric nervous system (ENS), and may contribute to the development of dyspepsia." (PMID 40081888, 2025).
eating disorder (1 paper, 2026). A broad group of psychological disorders with abnormal eating behaviors leading to physiological effects from overeating or insufficient food intake. "Use of GLP-1 and GLP-1/GIP medications for weight loss and interest in future use were also higher among those experiencing psychological distress and those reporting a history of eating disorders." (PMID 41501776, 2026).
emesis (1 paper, 2022). "The effects of blocking the GIPR in GIP- and T-2 toxin-induced emesis were evaluated." (PMID 35737050, 2022).
epilepsy (1 paper, 2025). A brain disorder characterized by episodes of abnormally increased neuronal discharge resulting in transient episodes of sensory or motor neurological dysfunction, or psychic dysfunction. "However, the exact involved pathophysiology mechanisms of GIP in epilepsy remained unclear." (PMID 40230662, 2025).